VN1R5 (vomeronasal 1 receptor 5 (gene/pseudogene))
Description:
Putative pheromone receptor.
Synonyms: V1RL5
Gene: Protein-coding gene on chromosome 1 (247,255,972 to 247,257,210, forward strand). Ensembl gene ENSG00000197617.
Subcellular location: Cell membrane
Genetic constraint (gnomAD): Missense variants: 302 observed, 373.11 expected, observed/expected ratio (o/e) 0.81, 90% interval 0.74 to 0.89. Synonymous variants: 133 observed, 140.51 expected, observed/expected ratio (o/e) 0.95, 90% interval 0.82 to 1.09.
Homologues: Orthologues: rabbit ORYCUNV1R1524 (31% identical), rat Vom1r84 (30% identical), rat Vom1r75 (30% identical), mouse Vmn1r1 (29% identical), mouse Vmn1r36 (29% identical), mouse Vmn1r37 (29% identical), mouse Vmn1r9 (29% identical), mouse Vmn1r11 (29% identical), mouse Vmn1r35 (29% identical), rat Vom1r73 (29% identical), rat Vom1r87 (29% identical), rat Vom1r81 (29% identical), and 72 more. Paralogues in human: VN1R4 (23% identical), VN1R1 (21% identical), VN1R2 (20% identical).
Diseases named in the same sentence as VN1R5 in open-access papers:
VN1R5 is named in the same sentence as 1 disease in open-access papers, as found by Europe PMC text mining. Sharing a sentence is not in itself a finding about the gene and the disease. The quoted sentences say what the papers report.
tumor (1 paper, 2013). "The function of FBN3, PCNXL3, SFXN3, SRGAP1, VN1R5 and WDR70 have been only marginally evaluated, and their role in the molecular signaling of tumor cells remains largely understudied." (PMID 23577124, 2013).